TRPV1 (transient receptor potential cation channel subfamily V member 1)
Diseases named in the same sentence as TRPV1 in open-access papers (continued):
Sharing a sentence is not in itself a finding about the gene and the disease.
chronic pancreatitis (6 papers, 2009 to 2023). A chronic inflammatory process causing damage and fibrosis of the pancreatic parenchyma. "The transient receptor potential vanilloid receptor 1 (TRPV1) gene has been associated with pain perception, and genetic variations in TRPV1 may modify the presence and phenotype of chronic pancreatitis." (PMID 20034385, 2009). "There is evidence that activation of TRPV1 is implicated in chronic pancreatitis." (PMID 20034385, 2009). "Allele frequencies of the 4 TRPV1 gene SNPs in chronic pancreatitis patients and healthy controls." (PMID 20034385, 2009). "TRPV1 expression is upregulated in pancreatic dorsal root ganglion neurons during chronic pancreatitis, and a significant reversal of pancreatic inflammation and pain relief was reported with systemic administration of the TRPV1 antagonist SB-366791." (PMID 36045746, 2022). "SN activation or administration of CGRP after the induction of inflammation causes exacerbation of the inflammatory response, and leads to functional failure, typical for the chronic pancreatitis, in the course of which there has been an increase of TRPV1." (PMID 28468316, 2017). "The aim of our study was to investigate the genetic variation of TRPV1 in Dutch patients with chronic pancreatitis and healthy controls." (PMID 20034385, 2009). "The aim of our study was to investigate the genetic variation of TRPV1 in Dutch chronic pancreatitis patients and healthy controls." (PMID 20034385, 2009). "Collectively, these data suggest a role for TRPV1 in chronic pancreatitis, and we hypothesized that TRPV1 could act as a modifier for chronic pancreatitis and that therefore genetic variations in TRPV1 could modify the presence and/or the phenotypical expression of chronic pancreatitis." (PMID 20034385, 2009). "And siRNA-mediated knockdown of TRPV1 diminishes spontaneous visceral pain in mice, whereas upregulation of TRPV1 expression and function by administration of the nerve growth factor (NGF) has been shown to promote pain in chronic pancreatitis." (PMID 25614752, 2014). "Moreover, systemic administration of the TRPV1 antagonist SB-366791 markedly reduced both visceral pain behavior and referred somatic hyperalgesia in rats with chronic pancreatitis, but not in control animals." (PMID 20034385, 2009).
cognitive decline (6 papers, 2018 to 2026). "Our findings provide novel insight into the network mechanisms underlying cognitive decline in AD and suggest TrpV1 activation as a novel therapeutic target." (PMID 30417826, 2018). "Moreover, while genetic variants are determined at birth, the cross-sectional design precludes causal inference between TRPV1 polymorphisms and cognitive decline in PD." (PMID 41568154, 2026). "These vascular effects are compounded by TRPV1’s role in the CNS, where it influences cognitive decline, neuroinflammation, and emotional regulation." (PMID 41463571, 2025). "The results of the present study provide both in vitro and in vivo evidence that TRPV1-mediated autophagy reduced amyloid and phosphorylated tau pathology and attenuated cognitive decline in a murine model." (PMID 35115924, 2021). "This supports the notion that aberrant TRPV1 signaling in both enteric and central circuits links gut dysbiosis to CNS complications in T1D, reinforcing its role in mediating mood disorders, cognitive decline, and the broader neuropsychological burden of autoimmune diabetes." (PMID 41463571, 2025). "This study suggests that capsaicin, a TRPV1 agonist, may be effective not only in promoting the swallowing reflex and as a potential AD treatment but also in patients with cognitive decline and difficulty with oral prosthetic therapy." (PMID 37299434, 2023). "In this study, we hypothesized that TRPV1-mediated microglial autophagy would reduce amyloid and phosphorylated tau pathology and attenuate cognitive decline in a mouse model." (PMID 35115924, 2021). "In the context of the neuronal relevance of mitochondrial functions, we hypothesize that it is possible to delay onset of age-related cognitive decline through metabolic SIRT1-dependent adaptation and improvement of mitochondrial function mediated by TRPV1 control." (PMID 30050571, 2018).
Glucose intolerance (6 papers, 2019 to 2024). Glucose intolerance (GI) can be defined as dysglycemia that comprises both prediabetes and diabetes. "In the present study, we found that WD intake caused glucose intolerance, oxidative stress, and impaired recovery of renal blood flow and renal function after I/R injury, which were exacerbated in TRPV1−/− mice compared to WT mice." (PMID 30834186, 2019). "Therefore, TRPV1 deficiency-induced glucose intolerance is likely attributed to impaired insulin secretion rather than oxidative stress." (PMID 30834186, 2019). "The main finding of this study is that pharmacological blockade of TRPV1 is capable of preventing, or even reversing, glucose intolerance in rodent models of T2DM." (PMID 31344877, 2019). "TRPV1 rs161364 and rs8065080 have a negative association with glucose intolerance (Song, Paik, Park, & Song, 2016), consistent with the present study." (PMID 32724612, 2020). "We propose that TRPV1 could be a promising therapeutic target in T2DM by improving glucose intolerance and correcting dysfunctional insulin secretion." (PMID 31344877, 2019). "The depletion of TRPV1 may lead to elevated glucose intolerance in T2DM." (PMID 37175192, 2023). "This may be also a reason why diet-induced glucose intolerance was exacerbated in TRPV1−/− mice." (PMID 30834186, 2019). "These correlations are consistent with the roles of unsaturated long-chain 2-MAGs including 2-AG, 2-DPG, and 2-DHG, as they may increase insulin sensitivity and decrease glucose intolerance through activation of CB2, TRPV1, and other targets." (PMID 36774515, 2023). "We found that TRPV1−/− mice had glucose intolerance even on a control diet, while urinary 8-isoprostane was normal compared to WT mice." (PMID 30834186, 2019).
hearing loss (6 papers, 2014 to 2025). "In aminoglycoside-induced hearing loss, TRPV1 mediates drug uptake, and inflammation exacerbates this toxicity by up-regulating TRPV1." (PMID 40688696, 2025). "Despite this, the involvement of inflammation in cisplatin-induced hearing loss was also found is closely related with TRPV1, as discussed in the following subsection." (PMID 40688696, 2025). "TS, a combination of Cuscutae Semen and Rehmanniae Radix Preparataan, its active ingredients including hyperoside, quercitrin, and kaempferol, can reduce drug and noise-induced hearing loss, potentially by downregulating TRPV1 in HEI-OC1 cells." (PMID 40688696, 2025). "In summary, TRPV1 plays a crucial role in various types of hearing loss, with its activation and up-regulation closely associated with inflammatory responses." (PMID 40688696, 2025). "In cisplatin-induced hearing loss, TRPV1 activation triggers inflammation via NOX3 and STAT1, further damaging hair cells." (PMID 40688696, 2025). "Accordingly, recent studies have demonstrated the association between Trpv1, Cacna1h, and Ngf genes and the development of sensorineural hearing loss." (PMID 37049613, 2023). "The genes Trpv1, Ngf, and Cacna1h, which have been reported to be closely related to hearing loss, were selected for analysis." (PMID 37049613, 2023). "The novelty of this observation is that this is the first time TNF-α mediated potentiation of TRPV1 mediated Ca2+ entry has been implicated in hearing loss." (PMID 31632242, 2019). "TRPV1 activation by cisplatin was therefore implicated in cisplatin-induced hearing loss, and indeed, reducing TRPV1 expression (by siRNA treatment) or TRPV1 activity (by capsazepine or ruthenium red) in the inner ear reduced cisplatin-induced hearing loss." (PMID 25106481, 2015). "The activation and upregulation of TRPV1 have been closely linked to hearing loss." (PMID 40688696, 2025). "Building on the established associations between TRPV1 and drug/noise-induced hearing loss, research into the role of TRPV1 in age-related hearing loss (ARHL) has yielded significant insights through the use of animal models and investigations into dietary and genetic-metabolic interactions." (PMID 40688696, 2025). "Additionally, TS was found to regulate several genes related to hearing loss, including Trpv1, Cacna1h, and Ngf, as determined by quantitative real-time polymerase chain reaction (RT-PCR) analysis." (PMID 37049613, 2023). "Recent studies have linked the genes Trpv1, Cacna1h, and Ngf with sensorineural hearing loss." (PMID 37049613, 2023). "In addition to drug-induced hearing loss, noise-induced hearing loss is also associated with TRPV1." (PMID 40688696, 2025). "Therefore, drugs which could modulate TRPV1 channel activity could be useful for the treatment of conditions ranging from chronic pain to hearing loss." (PMID 24861977, 2014). "Based on these observations, it was suggested that TRPV3 and TRPV4 play an important role in neuroprotection while TRPV1 and TRPV2 are involved in the pathology of hearing loss." (PMID 31866822, 2019). "Additionally, the up-regulation of TRPV1 following noise exposure is linked to increased levels of the inflammatory cytokine TNF-α, indicating its role in noise-induced hearing loss." (PMID 40688696, 2025).
hyperlipidemia (6 papers, 2013 to 2024). "In contrast, loss of the TRPV1 gene in Western-fed mice causes hyperlipidemia, and animals exhibit reduced locomotor activity with a more pronounced effect in males than in females." (PMID 38927688, 2024). "Many observations reported enhanced TRPV1 expression in metabolic disorders associated with hyperlipidemia while other observation reported suppression of TRPV1 expression in metabolic disorders." (PMID 36589466, 2022). "These two contradictory points of view will receive a special focus in this review in addition to shedding light on the role of Ca2+ in hyperlipidemia, the potential molecular mechanisms underlying TRPV1 regulation in lipid metabolism, and lipid mediators for TRPV1." (PMID 36589466, 2022). "Of note, atherosclerotic lesions were more pronounced in ApoE-knockout mice (ApoE−/−), a widely employed animal model for hyperlipidemia, upon further deletion of TRPV1 (ApoE−/− TRPV1−/−)." (PMID 32471282, 2020). "Like the WT animals, the TRPV1−/− mice with acute hyperlipidemia had significantly higher serum cholesterol concentration (P < 0.01)." (PMID 23935685, 2013). "TRPV1 WT mice and TRPV1−/− mice were used to establish a mouse model of acute hyperlipidemia." (PMID 23935685, 2013). "Four weeks of oral treatment with evodiamine (TRPV1 agonist) induced atheroprotection in ApoE−/− mice, but not in ApoE−/−/TRPV1−/− mice, by alleviating hyperlipidemia and systemic inflammation as well as hepatic macrovesicular steatosis." (PMID 32586044, 2020). "Transient receptor potential vanilloid 1 (TRPV1), a non-selective ligand-gated cation channel with high permeability for Ca2+, has received considerable attention as potential therapeutic target for the treatment of several disorders including pain, inflammation, and hyperlipidemia." (PMID 36589466, 2022).
liver cancer (6 papers, 2020 to 2026). An epithelial or non-epithelial malignant neoplasm that arises from the liver. "Regarding liver cancer, downregulation of TRPV1 is associated with poor prognosis; accordingly, TRPV1 activation disturbs Ca2+ homeostasis, leading to apoptosis in liver cancer cell lines." (PMID 41562849, 2026). "For example, increased expression of TRPV1 predicted the prolonged survival of patients with liver cancer." (PMID 35558077, 2022). "The overall survival rate in HCC patients with low expression of F2, GOT2, TRPV1, and the three-gene-combination F2-GOT2-TRPV1 were all significantly lower than that in liver cancer patients with high expression." (PMID 32547951, 2020). "The results of IHC for 90 liver cancer cases showed that the low protein expression of F2, GOT2, and TRPV1 was significantly associated with lower 5-year survival in HCC patients (F2: p = 0.033, GOT2: p = 0.035, TRPV1: p = 0.046; K-M survival analyses)." (PMID 32547951, 2020). "Capsaicin is an agonist of the transient receptor potential vanilloid subfamily 1 (TRPV1) and has been shown to exert protective effects on liver diseases, including liver injury, NAFLD, liver fibrosis and liver cancer." (PMID 39281271, 2024). "However, the activation of TRPV1 can increase MMP1 expression, which contradicts previous studies linking TRPV1 overexpression to longer disease-free survival in liver cancer patients." (PMID 37569884, 2023).
prostatitis (6 papers, 2014 to 2025). An infectious or non-infectious inflammatory process affecting the prostate gland. "RTX also desensitizes bladder nerves by reducing TRPV1 expression in the bladder, which helps alleviate lower urinary tract symptoms caused by prostatitis." (PMID 40070569, 2025). "Consequently, the intrinsic properties of the TRPV1 channel contribute to a lowered pain threshold within the sensory system associated with prostatitis, thereby intensifying the perception of pain." (PMID 39364048, 2024). "Inhibition of TRPV1 along the sensitization pathway may hold promise as a therapeutic approach for treating urinary dysfunction caused by prostatitis." (PMID 39544909, 2024). "Therefore, further elucidating the role of TRPV1 in prostatitis can enhance our understanding of the underlying mechanisms of this condition." (PMID 39364048, 2024). "This suggests that prostatitis may upregulate TRPV1 in DRG via the SP-NK-1 pathway, ultimately causing sensitization of internal organs and worsening bladder overactivity." (PMID 39544909, 2024). "Collectively, these results underscore the significant role of TRPV1 in bladder sensitization associated with prostatitis, suggesting that the inhibition of TRPV1 along this sensitization pathway could be a promising approach to treating urinary dysfunction linked to prostatitis in the future." (PMID 39544909, 2024). "Numerous animal studies have demonstrated that TRPV1 in the L6-S1 DRG plays a significant role in the sensitization of visceral organs in chronic prostatitis." (PMID 40070569, 2025). "Further research and clinical trials are needed to improve our understanding and utilization of the potential of TRPV1 channels to treat prostate disease." (PMID 39364048, 2024). "In this review, we provide a comprehensive overview of the current understanding of the role of TRPV1 in chronic prostatitis." (PMID 39364048, 2024). "In summary, the role of TRPV1 channels in prostate diseases holds significant research value and potential therapeutic applications." (PMID 39364048, 2024). "This highlights the importance of TRPV1 as a key target in prostatitis-induced bladder overactivity and as a necessary factor for NGF to drive bladder dysfunction." (PMID 39364048, 2024). "Preclinical data indicate that TRPV1 channels are significantly involved in the pathogenesis and progression of prostatitis." (PMID 39364048, 2024). "We observed that rats with prostatitis exhibited increased expression levels of SP, NK-1, and TRPV1 in the L6-S1 DRG." (PMID 39544909, 2024). "Recent studies have discovered that afferent neurons from the prostate and bladder come together in the L6-S1 DRG, bladder overactivity induced by prostatitis and alterations in TRPV1 in bladder afferent neurons rely on the activation of pelvic nerves." (PMID 39544909, 2024). "Future research should focus on more extensive zoological and pharmacological investigations to enhance our understanding of prostatitis pathogenesis and to develop new TRPV1 derivatives." (PMID 39364048, 2024). "The discussion focuses on the connection between TRPV1 and prostatitis pain and LUTS, and highlights the potential for targeting this channel in the development of novel treatment strategies." (PMID 39364048, 2024). "TRPV1 sensory nerves located in the prostate and perineal skin contribute to heightened pain sensitivity in individuals with chronic prostatitis/chronic pelvic pain syndrome." (PMID 39364048, 2024). "This article outlines the mechanism through which prostatitis induces pain and LUTS, with a specific focus on the role and potential therapeutic targets of TRPV1 in prostatitis." (PMID 39364048, 2024). "In recent years, some studies have indicated that the transient receptor potential vanilloid subtype 1 (TRPV1) channel is significant in the pathogenesis and progression of prostatitis." (PMID 39364048, 2024).